CIRBP (cold inducible RNA binding protein)
Diseases named in the same sentence as CIRBP in open-access papers (continued):
Sharing a sentence is not in itself a finding about the gene and the disease.
cancer (36 papers, 2006 to 2025). A tumor composed of atypical neoplastic, often pleomorphic cells that invade other tissues. "CIRBP, known for its ability to bind and post-transcriptionally regulate mRNA, has been linked to cancer promotion and inflammation." (PMID 37996875, 2023). "Previous studies suggest that CIRBP plays oncogenic roles by binding with specific mRNAs encoding cancer-associated proteins." (PMID 34490236, 2021). "As a stabilizing RNA-binding protein, CIRBP regulates multiple cancers through stabilizing specific mRNAs translating into cancer-associated proteins and modulating inflammation." (PMID 33287830, 2020). "The role of CIRBP in carcinogenesis appears to be mainly driven by its functions as an RNA binding proteins (RBPs), promoting the stability and translation of specific mRNAs encoding cancer-associated proteins." (PMID 34490236, 2021). "CIRBP is involved in controlling DNA repair and cell proliferation, and it plays a critical role in several human disorders, including cancer and inflammatory diseases." (PMID 39061186, 2024). "Previous studies have shown that CIRBP is regulated by miR-383-5p and facilitates the proliferation of cancer cells." (PMID 39030638, 2024). "Beyond ROS, our study of CIRBP-mediated OGFR regulation undoubtedly provides an alternative explanation for cardiotoxicity induced by cancer therapy." (PMID 35541895, 2022). "The results showed that the expression level of CIRBP in the cytoplasm of cancer tissues was significantly lower than that of adjacent tissues." (PMID 36061308, 2022). "Given the induction of cancer cell dormancy by DYRK1B in various cancer types, we also investigated the interactions between CIRBP and DYRK1B as well as the resulting impacts of these interactions on the tumourigenesis and chemoresistance of PDAC cells." (PMID 34490236, 2021). "Metastatic cancer cells have been shown to cycle between the brain parenchyma and leptomeningeal compartments in rodent models, with cold-inducible RNA-binding protein (CIRBP) and cyclooxygenase-2 representing candidate genes implicated in this process." (PMID 33578853, 2021). "Cold-inducible RNA binding protein (CIRBP) is a stress-responsive protein that promotes cancer development and inflammation." (PMID 33172965, 2021). "CIRBP, cold-inducible RNA-binding protein, belonging to the cold-shock protein family, is expressed in different cell types and was involved in various cancer pathological processes, including cell survival, cell proliferation, and cancer." (PMID 32984314, 2020). "Echoing the linkage between the mental gland and cancerous tumours, CIRBP is also part of the human telomerase complex and plays a crucial role in telomere maintenance." (PMID 31029098, 2019). "The RNA-binding motif protein 3 (RBM3) is a cold-inducible RNA-binding protein with broadly relevant roles in cellular protection, and putative functions in cancer and development." (PMID 29743635, 2018). "This review summarizes our current knowledge of cold-inducible RNA-binding protein and its actions, what we have yet to understand and its potential for use in treatment of diseases ranging from cancer to diabetes." (PMID 29134130, 2017). "Additionally, it has been documented that CIRBP plays a critical role in several human disorders, including cancer and inflammatory disease." (PMID 36358602, 2022). "The crucial function of CIRBP has been reported in various human diseases, including cancers." (PMID 36013308, 2022). "Cold-inducible RNA binding protein (CIRBP) plays promoting roles in several types of cancers, but its function remains unclear in PDAC." (PMID 34490236, 2021). "CIRBP, a cold-shock protein found in mammals, expressed in various cell types and is involved in multiple biological and cellular processes, such as cell survival, apoptosis, cell proliferation, circadian rhythm, immune response, reproduction, and cancer." (PMID 32184914, 2020).
cancer (continued). "CIRBP is known as a mediator of cancer-related inflammation and has been reported to act both as a tumour suppressor and a tumour promoter, depending on the cell type and cancer stage, while RACK1 plays an important role in the regulation of key signalling pathways in cancer." (PMID 31443305, 2019). "Likewise, we found that ephrin-B2 and CIRBP were expressed at lower levels in malignant tumours compared to benign tumours." (PMID 16969345, 2006). "Cold shock proteins such as the RNA-binding protein RBM3 and cold-inducible RNA-binding protein (CIRBP) are involved in diverse physiological and pathological processes, including circadian rhythm, inflammation, neural plasticity, stem cell properties, and cancer development." (PMID 40152901, 2025). "A significant prognostic marker and therapeutic target for cancer treatment may be CIRBP." (PMID 36358602, 2022). "Although quiescent cancer cells showed a relatively longer cycle of doubling time response to crowding microenvironmental conditions and depletion of critical nutrients or growth factors, we also confirmed that CIRBP overexpression promoted the proliferation of PDAC cells in vitro by colony assays." (PMID 34490236, 2021). "Moreover, it has been demonstrated that reduction of RBM3 expression – and expression of the highly homologous cold-inducible RNA binding protein (CIRP) – by heat shock impairs the survival of cancer cells and increases their sensitivity to chemotherapeutic compounds." (PMID 22145045, 2011). "Restoration of CIRBP and/or blunting OGF/OGFR signal are potential treatments for cardiotoxicity acquired from cancer therapies." (PMID 35541895, 2022). "Cold-inducible RNA-binding protein (CIRP), which is released by cold stimuli, and serum amyloid A (SAA), which is involved in TLR4-mediated cancer metastasis, also trigger TLR4 activation." (PMID 35712350, 2022). "According to the data, numerous genes (such as H2AFX, CDKN2A, TTF2, IKBKE, and UBE2I) were markedly upregulated in many cancer types, while some genes (such as ARRB1, LMO3, KHDRBS2, CIRBP, and RALYL) were remarkably downregulated in multiple cancer types." (PMID 35003212, 2021). "For example, CIRBP promotes telomere maintenance by increasing the levels of TERT mRNA, and enhances the tumorigenic properties of cancer cells by promoting the stability of HIF1α and cyclin E mRNAs." (PMID 33172965, 2021). "For example, cold-inducible RNA binding protein (CIRP, also known as CIRBP or A18 hnRNP) is a stress-induced protein involved in cancer." (PMID 33526057, 2021). "Among them, CIRBP is a TF which have the ability to control cellular response upon confronting a variety of cellular stresses, mediate neuroinflammation and regulate MAPK, Wnt, apoptosis and many cancer-related signaling pathways." (PMID 28719625, 2017). "The Cold-inducible RNA binding protein (CIRBP), a member of the glycine-rich RNA binding protein family, plays a role in several cellular processes including the regulation of gene expression, cell cycle control, and apoptosis in both inflammation and cancer contexts." (PMID 39030638, 2024). "However, a transcriptome-wide analysis of CIRBP mRNA targets in cancer has not yet been performed." (PMID 33172965, 2021). "Of note, four of the cancer genes present in the network (MAP2K2, E2F1, FZD2, and WNT7B), although absent from our high-confident list of CIRBP targets, are enriched in CIRBP IPs." (PMID 33172965, 2021).
tumor (29 papers, 2006 to 2025). "Here, we found that the expression of CIRBP was upregulated in PDAC tumor tissues and was significantly associated with poor prognosis." (PMID 34490236, 2021). "Clinicopathological analysis showed that high CIRBP expression was associated with large tumor size and worse histologic differentiation (P < 0.05)." (PMID 34490236, 2021). "We next analyzed the association between the CIRBP mRNA levels and the tumor stage of these BCa tissues, indicating that CIRBP expression levels were positively correlated with the T stage in BCa." (PMID 30315244, 2018). "Among the seven key MDRGs, CIRBP was downregulated in tumor tissues, while the other six genes were upregulated in tumor tissues." (PMID 40303346, 2025). "In intracranial tumors, CIRBP is overexpressed in tumor-adjacent areas compared to its expression in metastatic lesions in the brain." (PMID 39857625, 2024). "In vivo, tumor growth was significantly suppressed in the CIRBP knockdown group compared to the control group when the tumors were simultaneously treated with gemcitabine (P < 0.05)." (PMID 34490236, 2021). "Other proteins that interact with CIRBP and promote tumor invasion and chemoresistance remain to be explored." (PMID 34490236, 2021). "At the end point of the experiments, the tumor weight in the CIRBP overexpression groups was higher than that in the control group (P < 0.05)." (PMID 34490236, 2021). "A study also found the co-regulated expression of SFs in BRCA, indicating that CIRBP expressed much lower in tumor tissue than in metastatic tissue." (PMID 32984314, 2020). "CIRBP has been reported to be involved in multiple tumor progression via the activation of ERK and p38 MAPK7,42,43." (PMID 30315244, 2018). "Of note, recent studies have demonstrated an involvement of CIRBP in the proliferation of tumor cells and germ cells." (PMID 26927658, 2017). "As a sensor protein, which expression increases in response to stress, CIRBP plays important roles in tumor recurrence." (PMID 28355355, 2017). "Despite being primarily thought of as an oncogene, CIRBP may potentially play a part in tumor suppression." (PMID 36358602, 2022). "However, at the same time, some studies have shown that CIRBP is lowly expressed in nasopharyngeal carcinoma and colorectal cancer and can be used as a marker of tumor prognosis." (PMID 36061308, 2022). "Notably, CIRBP was originally considered as a tumor suppressor that inhibits tumor cell proliferation by prolonging the G1 phase of the cell cycle and participating in the DNA damage response." (PMID 34490236, 2021). "Similarly, ARGLU1 and CIRBP were lower expressed in tumor compared to metastatic tissue, while QKI was higher expressed." (PMID 30940821, 2019). "In tumor cells, CIRBP is highly expressed and thought to be an oncogene." (PMID 26927658, 2017). "The results showed that the expression of ACACB, ATP8B4, C14orf28, CIRBP, and DTWD1 were higher in normal tissues, and the content of CDC6, DSP, HMGB3, HNRNPA3P1, PPP1R14C, and TPX2 were higher in tumor tissues." (PMID 35778922, 2022). "The most significant target genes were putative tumor oncogenes/promoters (TK1, KIF2C, UBE2C, AURKB) and potential tumor suppressors (CALCOCO1, CIRBP, KLHDC1, CBX7)." (PMID 36358602, 2022). "It was found that only CIRBP, NCL, and HNRNPD are related to both mitochondrial function and autophagy, as well as anti-tumor biological activity." (PMID 36013308, 2022). "CIRBP overexpression promotes PDAC cell proliferation, migration, and invasion in vitro and tumor growth in vivo." (PMID 34490236, 2021). "Our results are consistent with the tumor suppressive capacities of CST3, as CIRBP promotes clonogenicity and anchorage-independent growth by down-regulating CST3 levels." (PMID 33172965, 2021).
tumor (continued). "Knockdown of CIRBP in PANC-1 and SW1990 cells inhibited proliferation, migration and invasion in vitro and suppressed tumor growth in vivo." (PMID 34490236, 2021). "Conversely, CIRBP knockdown in PANC-1 cells suppressed tumor growth in vivo, resulting in lower tumor weights than those of control tumors (P < 0.05)." (PMID 34490236, 2021). "Despite the relevance of CIRBP in tumor progression, no transcriptome-wide attempts have been done to identify CIRBP targets in a cancerous context." (PMID 33172965, 2021). "As a novel oncogene, CIRBP has been shown to increase the expression of HIF-1α by binding to the 3′-UTR of its mRNA, which suppresses the expression of prostaglandin I synthase (PTGIS) and regulates tumor progression." (PMID 34490236, 2021).
infection (12 papers, 2009 to 2025). The state of being infected such as from the introduction of a foreign agent such as serum, vaccine, antigenic substance or organism. "The activation of the ER-stress response during infection led to lower m6A modification of CIRBP, which resulted in alternative splicing of the transcript and reduced retention of an intron located downstream of the affected m6A peak." (PMID 37509095, 2023). "After infection with the adenovirus-carrying CIRBP gene for 24 h, rat primary cortical neurons were infected with another iAβ1-42 adenovirus containing the human Aβ1-42 sequence without any signal peptide for another 24 h." (PMID 32184914, 2020). "Importantly, this infection‐induced reduction in m6A modification of CIRBP transcripts modulates their alternative splicing, resulting in the down‐regulation of the long CIRBP isoform with intron retention, while the short isoform remains unaffected." (PMID 37850412, 2023). "Ectopic overexpression of both CIRBP-S and -L isoforms increased the infection by DENV, ZIKV and HCV, suggesting that CIRBP functions as a proviral gene in this context." (PMID 37509095, 2023). "The researchers found that the infection of HCV altered m6A modification of specific transcripts, including RIOK3 and CIRBP, and the changes in m6A in RIOK3 and CIRBP were partly caused by HCV-induced ER stress." (PMID 36560634, 2022). "In the context of infection by Flaviviridae, RIOK3 methylation, and CIRBP demethylation took place, and the changed m6A status promoted translation of RIOK3 and alternative splicing of CIRBP, respectively, all benefiting Flaviviridae infection consequently." (PMID 34975810, 2021). "Interestingly, these genes were not enriched for functional categories related to infection and included examples such as RIOK3, CIRBP, PER2, NOC2L, ALCAM, GOLGA3, and others." (PMID 37509095, 2023).
neurological diseases (4 papers, 2020 to 2026). "Our novel study shows the critical role of CIRBP in the progression of ferroptosis, and provides promising therapeutic target for hypoxia-induced neurological diseases." (PMID 38388728, 2024). "Taken together, these results indicate that attenuated expression of CIRBP may lead to neurological diseases and that the CIRBP binding element is likely located in regions corresponding to iron homeostasis-related genes." (PMID 38388728, 2024). "Exploring the role of CIRBP in spinal cord injury and the mechanism that triggers inflammation will not only bring hope to patients with spinal cord injury but also provide a reference for the treatment of other neurological disorders so that drugs targeting CIRBP can be developed for their benefit." (PMID 40036292, 2025). "Because our validation results for CIRBP indicated its potential role in RTT, it can be suggested that tissues other than neuronal tissues can be used to generate hypotheses related to neurological diseases." (PMID 32546682, 2020).
colon (1 paper, 2023). "Heterogeneous ribonuclear protein A18 (hnRNP A18), also known as cold inducible RNA binding protein (CIRBP) is an RNA binding protein (RBP) differentially upregulated in breast, melanoma, pancreatic, and colon solid tumors in response to low oxygen tension." (PMID 36539586, 2023).
neurodegenerative disease (1 paper, 2025). A disorder of the central nervous system characterized by gradual and progressive loss of neural tissue and neurologic function. "Consequently, CIRBP may represent a promising new target for the treatment of neurodegenerative diseases." (PMID 40779572, 2025).
CIRBP also shares sentences with these, for which no sentence is quoted: liver cancer (6 papers); chronic obstructive pulmonary disease (5); endometrial carcinoma (5); myocardial infarction (4); atrial fibrillation (3); Hypothermia (3); acute lung injury (2); acute pancreatitis (2); acute respiratory distress syndrome (2); brain injury (2); corticotroph adenoma (2); endothelial dysfunction (2); hemorrhage (2); infarction (2); injury (2); lymph node metastasis (2); Neonatal sepsis (2); osteoarthritis (2); ovarian tumor (2); pituitary adenoma (2); rectal carcinoma (2); acute coronary syndrome (1); acute myocardial infarction (1); adult-onset Still disease (1); alcohol use disorders (1); alopecia areata (1); amyotrophic lateral sclerosis (1); Arrhythmia (1); bacterial sepsis (1); benign tumours (1).
A further 43 diseases each share a sentence with CIRBP in 1 paper.